CXCL10 (C-X-C motif chemokine ligand 10)
Diseases named in the same sentence as CXCL10 in open-access papers (continued):
Sharing a sentence is not in itself a finding about the gene and the disease.
tumor (continued). "In ovarian cancer, synergistic effect of tumor‐associated IL‐17 and Th17 cells 66, as well as IL‐18‐primed “helper” NK cells 67, induced the production of endogenous CXCL9 and CXCL10 that were directly correlated with tumor‐infiltrating CD8+ T cells." (PMID 27726306, 2016). "A similar effect of EZH2 was observed in colorectal cancer, where targeting EZH2 in cancer cells also augmented the expression of CXCL9 and CXCL10 chemokines, affecting the infiltration of the tumor by effector T cells." (PMID 27793053, 2016). "In order to further elucidate the effect of CXCL10 on tumor inhibition, rabbit anti-murine CXCL10 antibody was used in the xenotransplant tumor model." (PMID 27764779, 2016). "Further, this study is likely to stimulate further research toward structurally related anti-tumor agents, for example, capable of inducing CXCL10 in tumor cells." (PMID 27551447, 2015). "Real-time PCR analysis showed that the mean expression levels of CXCL10 (120.2 ± 24.7) in the tumor tissues were significantly higher than the control (41.4 ± 11.6; P = 0.009)." (PMID 25605488, 2015). "We show that CCL2 is the main molecule produced in this DIO tumor model with chemotactic and tumor-promoting activities, followed by the chemokine IP-10 (CXCL10) and by the pro-tumor pro-inflammatory cytokine IL-6." (PMID 25599228, 2015). "Statistical analysis of those samples indicated that both CCL5 and CXCL10 expression (IHC scores) was significantly higher in tumor lesions versus marginal tissues (1.878 ± 1.679 vs. 0.588 ± 0.543, p < 0.0001; 2.472 ± 1.997 vs. 1.588 ± 1.042, p < 0.005)." (PMID 26317795, 2015). "A previous study in a mouse model of adoptive cell transfer demonstrated that blocking PD-1 increased the production of CXCL10 by bone marrow-derived myeloid cells, which enhanced the recruitment of CTLs in the tumor." (PMID 25354479, 2015). "Tumor-free induction by PMSB were mostly reversed by IFN-γ or IP-10/CXCL10 blockade and evidently deterred by MIG/CXCL9 or RANTES/CCL5 blockade (P < 0.05 versus controls)." (PMID 26512920, 2015). "The aim of the present study was to evaluate the anti-tumor effect of radiotherapy combined with CXCL10 gene therapy." (PMID 26622567, 2015). "The present results revealed that CXCL10 gene therapy and radiotherapy each attenuated tumor growth when administered separately." (PMID 26622567, 2015). "Immunohistochemical labeling of microvessels by CD31 in tumor sections revealed a decrease in tumor vessel density in the CXCL10 group and radiotherapy group compared with those in the control group." (PMID 26622567, 2015). "STAT1 also acts as a negative regulator of tumor angiogenesis partially through the induction of CXCL10." (PMID 26351076, 2015). "By contrast, the tumor growth rate in nude mice treated with CXCL10 gene therapy alone decreased compared with the control group, and this decline was more evident in the group treated with radiotherapy." (PMID 26622567, 2015). "A fusion between a tumor antigen and chemokine CXCL10 or CCL7 has been demonstrated to increase immune responses in immunized mice, and to protect against tumor challenge." (PMID 26257735, 2015). "Considering the changes in the frequency of T cell subsets in patients with tumor, we studied the expression of CXCL10 mRNA and found significant increases in the expression of this chemokine in the tumor sites." (PMID 25605488, 2015). "Over previous years, studies have increasingly reported that CXCL10 plays an important role in angiogenesis and tumor growth inhibition." (PMID 26622567, 2015). "These suggest that CXCL9 and CXCL10 are also the major chemokines that guide the adoptively transferred OT-I cells to the treated tumor." (PMID 25460506, 2015). "The appearance of spontaneous lung metastases in SCID mice inoculated with adenocarcinoma tumors occurred after that the CXCL10 levels from either the primary tumor or plasma had reached a nadir." (PMID 24971349, 2014).
tumor (continued). "The experiments revealed a stringent association of protein and mRNA expression levels of CXCL10 and STAT1 in the tumor." (PMID 24725474, 2014). "The assessment of the relative expression (tumour vs. normal paired tissue) revealed that CXCL10 was upregulated in 86% (85/99) of the cases." (PMID 24748971, 2014). "Treatments targeting CXCL10 therefore have to be used with care today, and it is important to fully understand the role of CXCL10 in individual tumour types and subgroups of tumours." (PMID 24395654, 2014). "We analyzed the concentration of CXCL10 in preoperative sera and tumor samples of 10 patients and compared these values with the expression levels of CXCL10 and STAT1 mRNA in the tumor." (PMID 24725474, 2014). "Among the STAT1 targets investigated in our study, MX1 and CXCL10 can be considered as genes influencing tumor progression, since their expression was significantly associated with bad patient‘s prognosis." (PMID 24725474, 2014). "Moreover, the administration of continuous intratumor injections of low dose, recombinant human CXCL10 (100 ng every other day) in adenocarcinoma tumors reduced both their size and metastatic potential, which was directly attributable to a reduction in tumor-associated angiogenesis." (PMID 24971349, 2014). "The only pro-angiogenic genes found up-regulated, and substantially, were that coding the chemokine IP-10/CXCL10 which was also strongly expressed in vivo by PC3 tumor from IL-27 treated animals, and the metalloproteinase inhibitor, TIMP3, in DU145 cells." (PMID 24681516, 2014). "The levels of CXCL10 in tumour tissue were significantly (P<0.001) higher compared to those in normal paired tissue." (PMID 24748971, 2014). "With respect to angiogenesis, IFN-γ is a potent inducer of several angiostatic chemokines, such as CXCL9 and CXCL10, from a variety of cells, including monocytes, macrophages, fibroblasts, endothelial cells, and tumor cells." (PMID 23533029, 2013). "CXCL10 is a chemokine for monocytes/macrophages, T cells, NK cells, and DCs; therefore, it is suggested that active NK cells were attracted to the tumor by CXCL10." (PMID 24369016, 2013). "Conversely, Cox2−/− mice and ASA-treated wild-type mice displayed enhanced expression of CXCL10 (C-X-C motif chemokine 10) and tumor-infiltration of CTLs." (PMID 24202450, 2013). "In order to assess the effect of the recombinant CXCL10 fusion proteins on lymphocyte recruitment, the purified proteins were injected into the center of each tumor and immune infiltrates were analyzed 4 h later." (PMID 24023642, 2013). "KGF also induced downregulation of a set of genes specifically upregulated in SCC cells compared to normal keratinocytes, including genes associated with tumor progression (MMP13, MATN2, CXCL10, and IGFBP3)." (PMID 22427941, 2012). "Several cytokine mRNAs' (CCL3/MIP-1α, CCL15/MIP-1δ, CXCL1, CXCL5/ENA78, CXCL8/IL8, CXCL9/MIG, CXCL10/IP10) were found to be overexpressed in the tumours while CCL15/MIP-1δ, CXCL5/ENA78 and IL8 mRNAs' were overexpressed in paired normals, as well." (PMID 21092330, 2010). "Among the few upregulated genes detected with quantitative RT-PCR, BCL7A has been classified as a tumor suppressor gene, while CXCL10 mediates a thymus-dependent antitumor response in vivo." (PMID 19123925, 2009). "Lastly, IP-10/CXCL10 inhibits tumor and endothelial cell growth and is inversely correlated with VEGF production." (PMID 18616824, 2008). "This was coupled with an increase in GM-CSF (two-fold, P<0.01), IFN-γ (4.2-fold, P<0.01), CXCL9 (1.4-fold, P<0.01), and CXCL10 (1.7-fold, P<0.05) within the tumour microenvironment." (PMID 16598185, 2006). "Moreover, Cxcl10 silencing significantly increased the burden of tumor cells disseminated to the lung." (PMID 41617729, 2026). "The results showed that the tumor growth in the CXCL10 OE group was significantly restricted." (PMID 41399390, 2026).
tumor (continued). "However, we observed CD103+ T and CXCL10 Macrophage co-localisation even when distant from the tumour border." (PMID 41542042, 2026). "Conversely, the lack of cytotoxic T-cell infiltration may be attributable to the epigenetic silencing of T helper 1 (TH1)-type chemokines like CXCL9 and CXCL10, which is known to create a ’cold’ tumor immune contexture (Nagarsheth, Wicha & Zou, 2017)." (PMID 41556056, 2026). "In particular, reduced TRPM5 activity leads to an increase in cytosolic Ca2+ concentration, which stimulates proliferative pathways and the production of inflammatory cytokines such as IL-6 and CXCL10, with particularly marked effects at the invasive edges of the tumor." (PMID 40507957, 2025). "Targeting CXCL10 therapeutically poses significant risks due to its dual role in tumor immunity." (PMID 40760734, 2025). "However, YAP depletion concomitantly abrogated the extracellular secretion of the chemokines Ccl5 and Cxcl10, which are key targets of type-I IFNs that promote tumor infiltration and activation of CTLs." (PMID 40542295, 2025). "Microglia also release specific chemokines, including CCL2 and CXCL10, which attract immune cells to the tumor site, though these chemokines may paradoxically contribute to an immunosuppressive tumor microenvironment under certain conditions." (PMID 39857798, 2025). "Strategies that increase CXCL10 expression or activate its CXCR3 receptor could enhance anti-tumor immunity by promoting effector cell recruitment to the tumor site." (PMID 41376630, 2025). "Hence, co-localisation of monocytes/macrophages and CD4+ T cells coincided with CXCL9/CXCL10 expression in human tumours." (PMID 40523200, 2025). "Previous studies established that the epigenetic modifier EZH2, which mediates H3K27 trimethylation and heterochromatin formation, can specifically repress the expression of Cxcl9 and Cxcl10 in several tumor entities, leading to the exclusion of cytotoxic T cells and NK cells from the TME29,30." (PMID 40562773, 2025). "Recent findings have elucidated that in gastric glandular cancer, regulated by IFN-γ/STAT1 signaling, the upregulation of CXCL10 correlates strongly with the degree of CD8+ T cell infiltration in the tumor microenvironment, thereby bolstering antitumor immunity." (PMID 40909948, 2025). "CXCL10 also reportedly contributes to the response to tumor development in several cancers." (PMID 40029556, 2025). "In the field of tumor therapy, Escherichia coli-derived bEVs have been shown to target and accumulate in tumor tissues, inducing the production of the anti-tumor cytokine CXCL10 and interferon-gamma (IFN-γ) and exerting their anti-tumor effects in an IFN-γ-dependent manner." (PMID 40308573, 2025). "In addition, the oHSV treatment resulted in higher expressions of Ccl4, Cxcl9, Ccl21 and Cxcl10 in the MC38 tumours." (PMID 39219056, 2025). "Additionally, ENKTL tumor cells can express DPP4, which cleaves CXCL2, CXCL9, and CXCL10, chemokines that recruit T cells and NK cells into the tumor microenvironment, depleting the number of anti-tumor effector cells." (PMID 41295262, 2025). "However, studies have shown that treatment with IFN-β or TGF-β blockade can polarize neutrophils to an “N1” antitumor phenotype, characterized by enhanced tumor cell phagocytosis and recruitment of T cells via CXCL10." (PMID 41219968, 2025). "Indeed, analysis of OS tumor databases reveals that high intra-tumoral expression of CXCL10 and/or CXCR3 correlates with improved prognosis, consistent with a robust local anti-tumor immune response." (PMID 41516196, 2025). "Studies have illustrated that CXCL10 plays a significant role during the early phases of hypoxia-induced inflammation, with its expression correlating positively with lymphocytic infiltration during tumor therapies." (PMID 40909948, 2025).
tumor (continued). "In these cases, CXCR3 antagonists ‎could be ‎used to block the tumor’s ability to use CXCL10 for immunosuppression, while in other ‎‎cases care must be taken to preserve the positive immune-activating effects of CXCL10." (PMID 40760734, 2025). "However, chronic inflammation and immune ‎‎dysregulation can lead to the persistent production of CXCL10, contributing to an ‎‎immunosuppressive microenvironment that favors tumor progression." (PMID 40760734, 2025). "2-HG limits the secretion of CXCL10 by tumor cells, reducing T cell recruitment to tumor sites." (PMID 40861464, 2025). "However, microglia also secrete critical cytokines such as interferon-γ (IFN- γ), IL-1, and IL-6, alongside chemokines like CCL2 and CXCL10, which modulate T cell activity and recruit immune cells to the tumor site." (PMID 39857798, 2025). "Disruption of PRMT5 was found to increase the secretion of chemokine CXCL10 by tumor cells." (PMID 41463372, 2025). "In addition, the efficient and sustained delivery of ‎ CXCL10 to ‎tumor cells remains a technical hurdle, especially in heterogeneous tumors with ‎‎different immune ‎profiles." (PMID 40760734, 2025). "Astaxanthin was associated with a higher quantity of tumor‐associated macrophages, infiltration of CD8+ T cells, Tumor Granzyme B, IL‐2, serum TNF‐α and interferon‐γ, genetic transcription of CXCL9, CXCL10, and CXCR3, and mRNA expression of cluster of differentiation." (PMID 40071130, 2025). "The type-1 interferon response leads to autocrine activation of IFNAR (interferon α/β receptors), resulting in CXCL9 (C-X-C motif chemokine ligand 9) and CXCL10 (C-X-C motif chemokine ligand 10) production, which subsequently stimulates T lymphocyte infiltration into the tumor." (PMID 40557162, 2025). "Despite this synergy, the functional outcomes of these pathways in response to CXCL10 are highly context-dependent and may differ between tumor types." (PMID 40760734, 2025). "Overall, the integration of CXCL10 signaling profiles with pathway-specific inhibitors represents a rational therapeutic strategy that allows clinicians to tailor treatments based on the molecular landscape of the tumor and immune context." (PMID 40760734, 2025). "It remains unclear whether the IFN-γ/STAT1 signaling regulates the immune escape for tumor progression demonstrated here by CXCL10/CXCR3." (PMID 40909948, 2025). "Conversely, a phase I/II clinical trial testing the durvalumab and olaparib combination showed minimal increase in both the STING protein and mRNA levels in post-treatment tumor biopsies, yet those samples had increase in CXCL10 and other immune mediators by RNA-seq." (PMID 39851178, 2025). "Similarly, Cxcl9 and Cxcl10 mRNA expression in murine RAW264.7 macrophages was also increased after coculture with IFN-β–treated Usp5-KO B16 tumor cells." (PMID 41321309, 2025). "However, cancer cells can exploit the MAPK/ERK ‎pathway to modulate CXCL10 and the immune microenvironment in a manner that promotes ‎tumor evasion and metastasis, complicating therapeutic strategies to inhibit tumor growth." (PMID 40760734, 2025). "CXCL10 is a secreted chemokine that is involved in trafficking of CXCR3-positive leukocytes, including CXCR3+ tumor associated CD8+ T cells and natural killer cells that promote tumor suppression as well as immunosuppressive CXCR3+ Tregs." (PMID 40589738, 2025). "The modest CXCL10 decrease in vitro likely reflects the limited complexity of the current experimental system, which cannot recapitulate the cellular diversity and signaling dynamics of the tumor microenvironment." (PMID 41463176, 2025). "Depletion of m6A demethylases, particularly ALKBH5, under hypoxia leads to the upregulation of CXCL10, which may impact tumor progression and immune response dynamics." (PMID 39824841, 2025).
tumor (continued). "The extent of overlap between CXCL9/CXCL10‐expressing and CCR7‐expressing tumour‐associated cDC1s, whether they represent end‐states or steps along the activation process and whether they have different functions, remains unclear." (PMID 40745918, 2025). "In addition, CXCL10 contributes to vascular normalization, a process that improves the infiltration of immune cells into the tumor and further enhances the efficacy of checkpoint blockade therapies." (PMID 40760734, 2025). "Furthermore, some results strongly suggest a protumoral role for human monocytes in B cell precursor ALL, orchestrated by CXCL-10 and its effect on tumor cell migration and invasion." (PMID 39996769, 2025). "CXCL10 levels increased linearly over time (p < 0.05), peaking at 6 weeks (3.17), which reinforces the notion of increasing effector T cell infiltration during tumor progression." (PMID 41278869, 2025). "Additionally, aCD40 enhanced tumoral production of CXCL9 and CXCL10, potent T cell chemoattractants that likely facilitated T cell trafficking from the periphery to the tumor microenvironment." (PMID 40585246, 2025). "This interaction facilitates angiogenesis and accelerates tumor progression, implying that the inhibition of miR-21-5p or the disruption of its interaction with CXCL10 could be effective in suppressing tumor growth and angiogenesis." (PMID 39944625, 2025). "Future targeted therapies could ‎include personalized ‎approaches that either enhance the immunostimulatory functions of CXCL10‎ or inhibit its tumor promoting effects." (PMID 40760734, 2025). "Nevertheless, at endpoint, CXCL10-expressing tumours showed significantly higher infiltration of total human leukocytes (p = 0.049) and CAR T cells (p = 0.01), indicating enhanced immune recruitment and CAR T cell trafficking driven by localized CXCL10 expression." (PMID 41366257, 2025). "Additionally, increased expression or secretion of CXCL10/11 has been shown to enhance tumor response to ICI immunotherapy." (PMID 40116486, 2025). "Furthermore, the increased CXCL10/11 expression likely contributes to enhanced recruitment of activated CD8+ T cells into the tumor." (PMID 40116486, 2025). "By enabling localized, sustained secretion of chemokines such as CXCL10 directly from tumour cells, this approach promotes immune cell recruitment and trafficking while avoiding systemic cytokine exposure, potentially minimizing off-target effects and toxicity." (PMID 41366257, 2025). "CXCL10 is an important chemokine that regulates the tumor immune microenvironment." (PMID 41640699, 2025). "CXCL10 may show tumor proliferative or anti-proliferative effects depending on the expression status and subtype (A vs. B) of its receptor CXCR3 on the target immune cell." (PMID 40295827, 2025). "HMGB1, on the other hand, activates the NF-κB pathway in Mφ via TLR4/RAGE signaling, promoting the secretion of chemokines such as CXCL9/CXCL10 and recruitment of effector T cells into the tumor microenvironment, while inhibiting Mφ polarization towards the M2 phenotype." (PMID 41019083, 2025). "Therefore, certain tumor cells with a high expression of CXCL10 and CXCR3 have stronger metastatic and invasive capabilities." (PMID 40145607, 2025). "CXCL9 and CXCL10 can be secreted by tumor cells and immune cells." (PMID 41332581, 2025). "While CXCL10 may contribute to tumor progression in certain contexts, particularly by recruiting immunosuppressive cells such as Tregs or M2-type macrophages, it is also a critical chemokine for orchestrating effective anti-tumor immune responses." (PMID 40760734, 2025). "We conclude that tumour-secreted CXCL10 and CXCL11 enhance CAR T cell migration." (PMID 41366257, 2025). "Additionally, several IFN‐stimulated genes (ISGs) were upregulated, including Ccl5 and Cxcl10, which are essential chemokines for attracting tumor‐infiltrating lymphocytes (TILs), indicating activation of the type I IFN pathway." (PMID 40135833, 2025).